ZNF189 (zinc finger protein 189)
Description:
May be involved in transcriptional regulation.
Tractability: PROTAC: UniProt records ubiquitination sites on it.
Gene: Protein-coding gene on chromosome 9 (101,398,851 to 101,410,660, forward strand). Ensembl gene ENSG00000136870.
Subcellular location: Nucleus
Subcellular location (Human Protein Atlas): Intermediate filaments
Pathways (Reactome):
Gene expression (Transcription): Generic Transcription Pathway
Gene Ontology:
Molecular function: DNA-binding transcription factor activity, RNA polymerase II-specific; RNA polymerase II cis-regulatory region sequence-specific DNA binding; sequence-specific DNA binding
Biological process: regulation of transcription by RNA polymerase II; negative regulation of transcription by RNA polymerase II; regulation of DNA-templated transcription
Cellular component: nucleus
Genetic constraint (gnomAD): Loss-of-function variants: 32 observed, 54.57 expected, observed/expected ratio (o/e) 0.59, 90% interval 0.44 to 0.79. The upper end of that interval is the gene's LOEUF score, 0.79, which puts it in group 3 of 6, group 1 being the genes least tolerant of losing a copy. Missense variants: 687 observed, 779.77 expected, observed/expected ratio (o/e) 0.88, 90% interval 0.83 to 0.94. Synonymous variants: 237 observed, 243.63 expected, observed/expected ratio (o/e) 0.97, 90% interval 0.87 to 1.08.
Homologues: Orthologues: chimpanzee ZNF189 (100% identical), macaque ZNF189 (99% identical), dog ZNF189 (99% identical), pig ZNF189 (98% identical), guinea pig ZNF189 (94% identical), rabbit ZNF189 (92% identical), rat Zfp189 (91% identical), mouse Zfp189 (91% identical). Paralogues in human: ZNF568 (46% identical), ZNF227 (45% identical), ZNF658 (45% identical), ZNF728 (45% identical), ZNF33B (45% identical), ZNF605 (44% identical), ZNF726 (44% identical), ZNF429 (44% identical), ZNF235 (44% identical), ZNF708 (43% identical), ZNF182 (43% identical), ZNF254 (43% identical), and 164 more.
Diseases named in the same sentence as ZNF189 in open-access papers:
ZNF189 is named in the same sentence as 4 diseases in open-access papers, as found by Europe PMC text mining. Sharing a sentence is not in itself a finding about the gene and the disease. The quoted sentences say what the papers report.
Immunodeficiency (1 paper, 2022). Failure of the immune system to protect the body adequately from infection, due to the absence or insufficiency of some component process or substance. "The best-matched TFs included ZNF460 and ZNF189, which are associated with lymphoma and immunodeficiency, respectively." (PMID 35752626, 2022).
major depression (1 paper, 2024). "Interestingly, in post-mortem tissue from human PFC (Brodmann area 25), individuals with major depression had lower expression of ZNF189 (human ortholog) mRNA than matched controls." (PMID 38272911, 2024). "Importantly, in post-mortem tissue from human PFC (Brodmann area 25), individuals with major depression had lower expression of ZNF189 mRNA than matched controls." (PMID 38272911, 2024).
orofacial clefting (1 paper, 2010). "In conclusion, with the possible exception of FLNB, HIC1 and ZNF189, our data suggest that maternal genes do not contribute significantly to orofacial clefting in the Norwegian and Danish samples." (PMID 20634891, 2010).
ZNF189 also shares sentences with these, for which no sentence is quoted: lymphoma (1 paper).